TMEM106B (transmembrane protein 106B)
Diseases named in the same sentence as TMEM106B in open-access papers (continued):
Sharing a sentence is not in itself a finding about the gene and the disease.
leukodystrophy (13 papers, 2021 to 2025). Leukodystrophies are a group of rare, progressive, metabolic, genetic diseases that affect the brain, spinal cord and often the peripheral nerves. "The only association to myelination and motor disease is with a rare dominant-negative mutation in TMEM106B (p.D252N), which leads to a loss of function of TMEM106B and a phenotype of hypomyelinating leukodystrophy." (PMID 40269985, 2025). "Recently, a hypomyelinating leukodystrophy with relatively mild phenotypes was attributed to a single de novo mutation in the gene encoding transmembrane protein 106B (TMEM106B) leading to a D252N residue change." (PMID 36003149, 2022). "More interestingly, a dominant D252N mutation in TMEM106B was recently identified as a cause of hypomyelinating leukodystrophy (HLD), a group of heritable neurodevelopmental disorders characterized by abnormal myelination in the central nervous system (CNS)." (PMID 35287730, 2022). "TMEM106B variants are known risk modifiers for FTD, while a single TMEM106B mutation is responsible for five unrelated cases of hypomyelinating leukodystrophy." (PMID 33802612, 2021). "In addition to these neurodegenerative diseases, a dominant coding mutation in the lumenal domain of TMEM106B, D252N, was shown to cause hypomyelinating leukodystrophy (HLD)." (PMID 40451428, 2025). "Furthermore, a novel dominant D252N mutation in TMEM106B causing an amino acid substitution has been recently associated with several cases of hypomyelinating leukodystrophy (HLD)." (PMID 38710967, 2024). "Besides these genetic associations/ risk alleles, a dominant mutation (D252N) in TMEM106B causes hypomyelinating leukodystrophy in rare cases." (PMID 36707901, 2023). "The precise biochemical function of TMEM106B is unknown, however a dominantly inherited amino acid substitution (D252N) in the protein causes hypomyelinating leukodystrophy and myelination defects are observed in TMEM106B knockout mice." (PMID 37726834, 2023). "The D252N leukodystrophy mutation resides within the amyloidogenic region in TMEM106B (residues 120–254), but it is unclear whether the D252N mutation could be more amyloidogenic than wildtype TMEM106B." (PMID 36003149, 2022). "Mutation in TMEM106B are cause of leukodystrophy, hypomyelinating, 16 (MIM 617964) autosomal dominant neurologic disorder characterized by onset of hypotonia, nystagmus, mildly delayed motor development in infancy and degeneration of the white matter in the brain." (PMID 33613193, 2021). "A heterozygous D252N mutation in TMEM106B causes hypomyelinating leukodystrophy (HLD), a group of heritable neurodevelopmental disorders characterized by abnormal myelination in the central nervous system (CNS)." (PMID 37146150, 2023). "Since TMEM106B mutation is associated with hypomyelinating leukodystrophy (HLD) and TMEM106B deficiency in mice causes myelination defects, we examined myelination defects in the cerebellum of Tmem106b−/− mice." (PMID 35287730, 2022). "To date, the exact mechanism through which TMEM106B variants are linked to hypomyelinating leukodystrophy and FTD risks remains to be fully elucidated, although studies have suggested that it involves TMEM106B-mediated lysosomal regulation/transport." (PMID 33802612, 2021). "If challenged in experimental models for de- and remyelination, Tmem106b−/− knockout mice show deficits in the process of axonal remyelination, compatible with the finding of a dominant TMEM106B mutation as the underlying cause for a rare form of hypomyelinating leukodystrophy." (PMID 36707901, 2023). "Furthermore, a dominant mutation (D252N) in TMEM106B was found in a patient with hypomyelinating leukodystrophy (HLD), a group of genetic disorders that affect the development of the myelin sheath in the brain, suggesting a role of TMEM106B in myelination." (PMID 40713630, 2025).
leukodystrophy (continued). "TMEM106B is one of the genes that straddle the genetic spectrum of FTD and leukodystrophy, and knock-down of its expression appears to have a protective role in myelination." (PMID 33802612, 2021).
tauopathy (11 papers, 2021 to 2025). Neurodegenerative disorders involving deposition of abnormal tau protein isoforms (tau proteins) in neurons and glial cells in the brain. "For instance, one risk variant (rs1990622) is implicated in the pathologic presentation of AD, and genetic editing of the risk allele to a protective allele of TMEM106B rescued cognitive decline and neurodegeneration in an animal model of tauopathy." (PMID 39606446, 2024). "The mechanistic drivers of TMEM106B proteinopathy appear distinct from known modifiers of tauopathy." (PMID 39711302, 2025). "This agrees with previous studies which have shown that TMEM106B forms neuronal aggregates patients with AD and other tauopathies." (PMID 39606446, 2024). "Nevertheless, we find a consistent correlation between TMEM106B and pTau burden in both human disease and an in vivo model of tauopathy." (PMID 39606446, 2024). "Taken together, these findings reaffirm prior studies describing TMEM106B aggregation in human tauopathies." (PMID 39606446, 2024). "TMEM106B filaments have also been observed in the brains of individuals with tauopathies and α-synucleinopathies, as well as in the brains of neurologically normal individuals." (PMID 37532939, 2023). "Recent studies have shown that complete loss of TMEM106B exacerbates tau pathology and tau-mediated neurodegeneration in the PS19 tauopathy mouse model, while the T185S protective variant protected against cognitive deficits and neurodegeneration without affecting tau pathology." (PMID 40713630, 2025). "The role of TMEM106B in tauopathy has been also explored in mouse models." (PMID 40713630, 2025). "We found that genetic knockout of spop-1, sut-2, and sut-6 resulted in weak to no rescue of proteinopathy phenotypes, indicating that the mechanistic drivers of TMEM106B proteinopathy may be distinct from tauopathy." (PMID 38915598, 2024). "Additionally, genetic manipulation of TMEM106B expression in murine models of tauopathy have revealed a potentially significant role of TMEM106B in tau-related neurodegenerative diseases." (PMID 39606446, 2024). "Thus, we next investigated TMEM106B phenotypes in human tauopathy using two different disease cohorts: AD and AD with limbic-predominant age-related TDP-43 encephalopathy (AD/LATE)." (PMID 39606446, 2024). "However, other studies have shown that TMEM106B filaments accumulate in the human brain in an age-dependent manner in many neurodegenerative conditions, including tauopathies and synucleinopathies, as well as in neurologically normal individuals." (PMID 37532939, 2023). "Several other studies also identified TMEM106B fibrils in diverse neurodegenerative diseases such as FTLD-TDP, tauopathy, AD, and α-synucleinopathy, and normal aging, indicating that TMEM106B fibrils are a previously unappreciated common protein aggregation that exists in the brain." (PMID 37563705, 2023). "Additionally, our data showed that in both PS19 murine model and postmortem tissues from AD and AD/LATE patients, phosphorylated tau burden correlated positively with TMEM106B immunoreactivity, possibly suggesting a conserved role that TMEM106B plays in tauopathy." (PMID 39606446, 2024). "In addition, very recent work indicated that brain samples from TDP-43 proteinopathies as well as tauopathies and synucleinopathies are characterized by amyloid fibrils consisting of a 135-amino acid C-terminal fragment of transmembrane protein 106B (TMEM106B)." (PMID 36385948, 2022). "However, a rigorous analysis of the histological pattern of endogenous TMEM106B in early- and late-stage murine models of tauopathy has not yet been conducted." (PMID 39606446, 2024).
Cognitive impairment (9 papers, 2015 to 2024). Abnormal cognition is characterized by deficits in thinking, reasoning, or remembering. "As in earlier studies, LATE-NC was associated with HS, older age, cognitive impairment, and the TMEM106B risk genotype." (PMID 35366087, 2022). "In addition TMEM106B has been associated with inflammation, neuronal loss, and cognitive deficits, even in the absence of known brain disease, and their impact is highly selective for the frontal cerebral cortex of older individuals." (PMID 30863397, 2019). "However, variation in TMEM106B does not change the risk for ALS, but among those with ALS, it is associated with the presentation of cognitive impairment." (PMID 30390709, 2018).
proteinopathy (9 papers, 2014 to 2025). "Thus, the CT domain of TMEM106B should be considered a pathogenic protein, and the concept of TMEM106B proteinopathy warrants further analysis both in the context of age‐related changes to TMEM106B and multi‐proteinopathy disorders." (PMID 39711302, 2025). "However, it remains to be determined whether TMEM106B fibrils are more frequently associated with certain proteinopathies, which will require detailed unbiased studies of large cohorts." (PMID 36056242, 2022). "We expect lysosomal dysfunction induced by loss of PGRN impairs TMEM106B processing, resulting in aggregation and TMEM106B proteinopathy." (PMID 38915598, 2024). "Understanding the aggregation propensity of TMEM106B as well as the neurodegenerative potential of TMEM106B fibrillization requires new animal and cellular models of the TMEM106B proteinopathy occurring in aging related neurodegenerative disease." (PMID 38915598, 2024). "New findings in cryo-EM analysis in 2022 from three research groups suggest a potential etiologic commonality of transmembrane protein 106B (TMEM106B) among distinct proteinopathies." (PMID 38255218, 2024). "Herein, we describe the first live organism transgenic model of TMEM106B C-terminal proteinopathy generated by expressing the TMEM106B C-terminal aggregation prone fragment constituting the fibrillar core in FTLD cases." (PMID 38915598, 2024). "Because TMEM106B is identified as a direct target for TDP-43-regulated gene expression, the cytoplasmic sequestration of TDP-43 in TDP-43 proteinopathy might induce deregulated expression of TMEM106B in neurons containing TDP-43-positive inclusions." (PMID 24684749, 2014). "TMEM106B has also been shown to modify TDP-43 pathology in human ALS brain and cell-based models of TDP-43 proteinopathy." (PMID 35287730, 2022). "Cyro-EM studies have found that TDP-43 inclusions in FTLD-TDP are primarily composed of TMEM106B protein filaments, a feature that may also be present in many TDP-43 proteinopathies." (PMID 41264095, 2025). "The association of the TMEM106B haplotype with residual cognition is plausible, as TDP-43 proteinopathy was not considered in our model to derive residual cognition." (PMID 28441426, 2017).
lung cancer (7 papers, 2018 to 2026). A malignant neoplasm involving the lung. "For instance, TMEM106B has been shown to be a valuable marker of lung cancer metastasis, whereas COL10A1 plays a diagnostic role of circulating extracellular matrix-related proteins." (PMID 31640282, 2019). "TMEM106B::ROS1 has previously been found in non–small cell lung cancer, and the resulting fusion protein contains a ROS1 tyrosine kinase domain with assumed oncogenic activity." (PMID 38877653, 2024). "TMEM106B modulates the expression of the CLEAR network lysosomal genes in lung cancer cells in a TFEB-dependent manner, and drives lung cancer metastasis." (PMID 33292395, 2020). "In the study reported here, we identify TMEM106B as a primary robust driver of lung cancer metastasis." (PMID 30013069, 2018). "Our data here identify a novel function of TMEM106B, where its expression in lung cancer cells stimulates the production of enlarged lysosomes and increased synthesis of lysosomal hydrolases that are packaged into the lysosomes." (PMID 30013069, 2018). "Among others, we identified TMEM106B as one of the most robust drivers of lung cancer metastasis in vivo." (PMID 30013069, 2018). "Here the authors characterize the role of TMEM106B in driving metastatic lung adenocarcinoma and suggest that TMEM106B-mediated secretion of cathespin impacts cell migration and invasion of lung cancer cells, increasing metastatic spreading." (PMID 30013069, 2018). "This is the first report that elaborates the novel connection between TMEM106B overexpression in lung cancer cells and elevated lysosome production." (PMID 30013069, 2018). "TMEM106B deregulates lysosome function by affecting lysosomal synthesis and exocytosis in lung cancer cells, thus resulting in increased release of lysosomal cathepsins into the extracellular matrix, leading to cellular invasion and metastasis." (PMID 30013069, 2018). "GEPIA data link high TMEM106B mRNA expression to poor OS in lung cancer patients." (PMID 41596760, 2026). "Since TMEM106B has been shown to regulate TFEB activity in neuronal cells, we wanted to determine whether TMEM106B similarly regulates TFEB in a manner that is required for TMEM106B-driven phenotypic changes in lung cancer cells." (PMID 30013069, 2018). "Our data outline a novel mechanism for TMEM106B-mediated metastasis in lung cancer." (PMID 30013069, 2018). "To determine whether lung cancer cells with induced TMEM106B expression show increased lysosomal exocytosis, we co-expressed RFP-tagged LAMP1 in the cells expressing GFP-tagged TMEM106B or GFP as control." (PMID 30013069, 2018). "This is the first report of a mechanistic link demonstrating how TMEM106B could drive lung cancer metastasis by deregulating lysosome function." (PMID 30013069, 2018). "Here, we have identified TMEM106B as a novel and specific driver of lung cancer metastasis." (PMID 30013069, 2018). "Machine learning analysis ranks TMEM106B at the top for separating obstructive sleep apnea (OSA) and lung cancer from controls." (PMID 41596760, 2026). "Overexpression of TMEM106B has been reported to induce nuclear translocation of TFEB and expression of TFEB-regulated lysosomal genes in HEK293 cells, primary cortical neurons, and lung cancer cells." (PMID 40713630, 2025). "In a TFEB-dependent manner, TMEM106B could modulate the expression of lysosomal genes of the coordinated lysosomal expression and regulation (CLEAR) pathway in lung cancer cells and patient samples." (PMID 30013069, 2018).
lysosomal storage disease (6 papers, 2020 to 2024). A metabolic disorder caused by mutations in proteins critical for lysosomal function, including lysosomal enzymes, lysosomal integral membrane proteins, and proteins involved in the post-translational modification and trafficking of lysosomal proteins. "In lysosomal storage diseases, the inability to degrade substrates causes a massive increase in lysosomes size, and lysosomes are also increased in size in response to TMEM106B overexpression." (PMID 39596848, 2024). "Since localization to lysosomes is important for progranulin function and loss of progranulin could lead to lysosome storage disease, it is possible that TMEM106B and GRN mutations both contribute to the development of FTD via worsening lysosome functions." (PMID 37563705, 2023). "In vivo, TMEM106B has opposing effects in mouse models of lysosomal diseases where it was found that TMEM106B differentially modulates the progression of the lysosomal storage diseases Gaucher disease and neuronal ceroid lipofuscinosis." (PMID 37443768, 2023). "Increased levels of TMEM106B are also reported in models of lysosomal storage disorder." (PMID 37563705, 2023). "These phenotypes are reminiscent of features exhibited by lysosome storage diseases and further corroborate the critical roles of PGRN and TMEM106B in the lysosome." (PMID 32852886, 2020). "Lysosomes hold potential as an attractive target for therapeutic intervention in ALS, as in addition to VCP, several other ALS associated genes have a role in lysosomal homeostasis (C9orf72, TARDBP, TMEM106B, TBK1, OPTN, SQSTM1) and several lysosomal storage diseases manifest neurological features." (PMID 39593143, 2024).
cognitive decline (4 papers, 2017 to 2024). "Importantly, and in contrast to some of the published literature, 18 31 there is no clear beneficial effect of the putative protective alleles in UNC13A and TMEM106B on cognitive decline, either among those with or without the C9ORF72 repeat expansion." (PMID 37827570, 2024).
synucleinopathies (4 papers, 2022 to 2023). "We initially observed TMEM106B filaments in the brains of individuals with familial and sporadic tauopathies, Aβ amyloidoses, synucleinopathies and TDP-43 proteinopathies." (PMID 35344985, 2022).
amyloid (3 papers, 2022 to 2025). "In addition to Aβ and α-synuclein, tau, TDP-43, and fragments of TMEM106B are also commonly present in amyloid deposits in various neurodegenerative disease." (PMID 39827271, 2025).
Anxiety (3 papers, 2018 to 2025). Intense feelings of nervousness, tension, or panic often arise in response to interpersonal stresses. "Increased TMEM106B levels led to altered synaptic signaling in 12-month-old animals which further exhibited an anxiety-like phenotype." (PMID 40269985, 2025). "Together with the increase in the amount of time spent in the closed arms of the EPM, this indicates that mice overexpressing TMEM106B have an anxiety-like phenotype at 12-months of age." (PMID 40269985, 2025). "However, neither partial nor complete reduction of Tmem106b altered the anxiety phenotype observed in 66R-injected wild-type mice as determined by the open field assay or fear conditioning tests." (PMID 29855382, 2018).
COVID-19 (3 papers, 2023 to 2025). A disease caused by infection with severe acute respiratory syndrome coronavirus 2. "Interestingly, the high expression of TMEM106B expression in the brain compared to the lung might contribute to neurological symptoms such as stroke, brain hemorrhage and memory loss in COVID-19 patients." (PMID 37520399, 2023). "Vimentin, CD147, and TMEM106B have been identified as co-receptors or alternative receptors, though role of TMEM106B in COVID-19 pathology lacks experimental validation." (PMID 39967675, 2025). "Therefore, TMEM106B targeting may prevent neurological symptoms associated with COVID-19." (PMID 37520399, 2023). "We previously observed a correlation between SARS-CoV-2 infection and elevated TMEM106B expression in epithelial airway cells from COVID-19 patients." (PMID 37421949, 2023). "Further establishing TMEM106B as a relevant host factor in COVID-19 will require blocking TMEM106B function in animal models, along with an extensive analysis of the viral tropism and pathology caused by SARS-CoV-2 infection." (PMID 37421949, 2023). "Finally, single-cell transcriptome analyses of different tissues from COVID-19 patients to correlate viral RNA levels with host gene expression could shed more light on the in vivo relevance of TMEM106B and other candidate receptors for SARS-CoV-2 infection." (PMID 37421949, 2023). "Thus, TMEM106B may facilitate virus entry into specific ACE2-negative cell types or tissues, possibly contributing to the multi-organ pathology seen in COVID-19." (PMID 37421949, 2023). "Furthermore, overexpression of TMEM106B specifically enhances cell entry by pseudoviruses carrying SARS-CoV-2 spike protein, and it has been observed that TMEM106B has a high-level expression in airway epithelium from patients with COVID-19 compared to non-infected patients." (PMID 37520399, 2023).
colorectal cancer (2 papers, 2021 to 2024). A primary or metastatic malignant neoplasm that affects the colon or rectum. "Concurrently, MAGI2-AS3 advances the progression of colorectal cancer by manipulating the miR-3163/TMEM106B axis." (PMID 39336798, 2024).